BRMS1 (BRMS1 transcriptional repressor and anoikis regulator)
Description:
Transcriptional repressor. Down-regulates transcription activation by NF-kappa-B by promoting the deacetylation of RELA at 'Lys-310'. Promotes HDAC1 binding to promoter regions. Down-regulates expression of anti-apoptotic genes that are controlled by NF-kappa-B. Promotes apoptosis in cells that have inadequate adherence to a substrate, a process called anoikis, and may thereby inhibit metastasis. May be a mediator of metastasis suppression in breast carcinoma.
Synonyms: DKFZP564A063
Tractability: PROTAC: UniProt records ubiquitination sites on it; ubiquitination databases record sites on it; its protein half-life has been measured.
Gene: Protein-coding gene on chromosome 11 (66,337,333 to 66,345,132, reverse strand). Ensembl gene ENSG00000174744.
Subcellular location: Nucleus; Cytoplasm
Subcellular location (Human Protein Atlas): Centrosome
Pathways (Reactome):
Chromatin organization: HDACs deacetylate histones
Disease: Potential therapeutics for SARS
Gene Ontology:
Molecular function: NF-kappaB binding; protein binding; histone deacetylase binding
Biological process: negative regulation of DNA-templated transcription; positive regulation of anoikis; positive regulation of protein deacetylation; regulation of apoptotic process; negative regulation of cell migration; negative regulation of stem cell population maintenance; negative regulation of transcription by RNA polymerase II; negative regulation of transforming growth factor beta receptor signaling pathway; positive regulation of stem cell population maintenance
Cellular component: cytoplasm; nucleus; nucleoplasm; Sin3-type complex
Genetic constraint (gnomAD): Loss-of-function variants: 26 observed, 41.26 expected, observed/expected ratio (o/e) 0.63, 90% interval 0.46 to 0.87. The upper end of that interval is the gene's LOEUF score, 0.87, which puts it in group 3 of 6, group 1 being the genes least tolerant of losing a copy. Missense variants: 289 observed, 318.36 expected, observed/expected ratio (o/e) 0.91, 90% interval 0.82 to 1. Synonymous variants: 103 observed, 122.2 expected, observed/expected ratio (o/e) 0.84, 90% interval 0.72 to 0.99.
Homologues: Orthologues: chimpanzee BRMS1 (100% identical), guinea pig BRMS1 (98% identical), rat Brms1 (94% identical), mouse Brms1 (93% identical), macaque BRMS1 (87% identical), pig BRMS1 (85% identical), tropical clawed frog brms1 (66% identical), zebrafish brms1 (59% identical), Drosophila melanogaster Brms1 (38% identical). Paralogues in human: BRMS1L (55% identical), SUDS3 (24% identical).
Diseases named in the same sentence as BRMS1 in open-access papers:
BRMS1 is named in the same sentence as 51 diseases in open-access papers, as found by Europe PMC text mining. Sharing a sentence is not in itself a finding about the gene and the disease. The quoted sentences say what the papers report.
breast carcinoma (64 papers, 2007 to 2026). "It has also been demonstrated that loss of or decrease in BRMS1 expression is present in several human tumors, such as breast cancer." (PMID 37687058, 2023). "Breast Cancer Metastasis Suppressor 1 (BRMS1) expression is associated with longer patient survival in multiple cancer types." (PMID 34788285, 2021). "Following a stringent inclusion and exclusion criteria, case–control studies with associations between BRMS1 and breast cancer were selected from articles obtained by way of searches conducted through an electronic database." (PMID 28533425, 2017). "BRMS1 is one of the most frequently mutated tumor suppressors in human cancer including breast cancer." (PMID 26544623, 2015). "In our current study, we elucidate the underlying mechanism by which BRMS1 attenuates breast cancer cell invasion." (PMID 26520789, 2015). "We next determined the underlying mechanism by which BRMS1 inhibits TGF-β1-induced breast cancer cell EMT." (PMID 26520789, 2015). "It differs from the study involving BRMS1 immunoexpression in breast cancer, which showed that the loss of BRMS1 protein expression predicts reduced disease-free survival." (PMID 24688598, 2014). "Promoter analysis of the BRMS1 gene indicated that epigenetic silencing contributes to the reduction or loss of BRMS1 expression in breast carcinoma and non-small-cell lung cancer." (PMID 22927944, 2012). "In a subgroup of patients suffering from breast cancer, loss of tumor expression of BRMS1 protein was associated with reduced disease-free survival." (PMID 22356677, 2012). "DNA methylation contributes to the downregulation of breast cancer metastasis suppressor gene 1 (BRMS1), while demethylation has been shown to inhibit the invasion of breast cancer cells." (PMID 40149562, 2025). "The potential involvement of ARID4B in breast cancer was first suggested by the physical interaction between ARID4B and BRMS1 (breast cancer metastasis suppressor)." (PMID 40558499, 2025). "BRMS1, located on chromosome 11q13, was first identified in the 1990s following clinical observations linking deletions in chromosome 11 to increased breast cancer aggressiveness and reduced overall survival in patients 230,231." (PMID 40521202, 2025). "Breast Cancer Metastasis Suppressor 1 (BRMS1) is a tumor metastasis suppressor gene discovered in breast cancer cells in 2000." (PMID 39143438, 2024). "When repressed in metastatic breast cancer cells, BRMS1 decreased lung and lymph node metastasis in experimental and spontaneous metastasis assays." (PMID 37296870, 2023). "BRMS1 is a metastasis suppressor that affects several stages of the breast carcinoma metastasis cascade, acting through different mechanisms involving different genes whose function is related to the control of metastatic potential." (PMID 37628949, 2023). "For example, Breast Carcinoma Metastasis Suppressor gene 1 (BRMS1) was found to be a core component of the LSD1-CoREST complex, using these interactions to suppress breast cancer migration and invasion." (PMID 35687133, 2022). "It promotes breast cancer tumorigenesis by activating ERα-target genes or repressing BRMS1 expression and protects breast cancer cells from immune surveillance by repressing type I interferons and interferon-stimulated genes." (PMID 35805040, 2022). "The protein of interest in this study, Breast Cancer Metastasis Suppressor 1 (BRMS1), is a metastasis suppressor, which is defined by the ability to suppress metastasis without blocking primary tumor growth." (PMID 34788285, 2021). "In support of our results, previous reports have demonstrated that an inverse correlation exists between BRMS1 and miR-31 expression, disease development, and lengthy survival of people suffering from breast cancer." (PMID 32405371, 2020). "SNX1b and its homologues participate in breast cancer tumorigenesis by mediating BRMS1-dependent transcriptional repression." (PMID 31480430, 2019).
breast carcinoma (continued). "The process of migration and invasion are an important step in the metastasis of breast cancer, and these processes can be regulated by a variety of factors such as BRMS1, E-cadherin, CXCL12, MMP9, Orai1, Stim1, TGF-β, and VEGF." (PMID 29316690, 2018). "The BRMS1-expressing cells showed increased levels of Cx43 but reduced Cx32, leading to loss of GJIC between breast cancer cells and between them and breast epithelial cells." (PMID 29865195, 2018). "An in vivo murine study revealed that metastatic breast cancer cells in the bone formed more active GJs with osteoblasts than with themselves and BRMS1 expression increased homotypic GJIC." (PMID 29865195, 2018). "Increasing evidence has shown that the process of migration and invasion plays key roles in breast cancer metastasis and that these processes can be regulated by a variety of factors, such as BRMS1, E-cadherin, and VEGF." (PMID 29316690, 2018). "In another study, GJIC was restored in the same metastatic breast cancer cell line upon ectopic expression of the breast cancer metastasis suppressor gene BRMS1." (PMID 29865195, 2018). "They found that higher BRMS1 expression was correlated with better prognosis and overall disease-free survival in breast cancer." (PMID 29254284, 2017). "Results of our meta-analysis suggested that BRMS1 protein in breast cancer tissues was significantly lower in comparison with normal breast tissues (odds ratio, OR = 0.08, 95% confidence interval (CI) = 0.04–0.15)." (PMID 28533425, 2017). "There was heterogeneity in expression of BRMS1 mRNA between breast cancer and normal tissues, thus a fixed-effect model was performed (P < 0.001, I2 = 99.5%)." (PMID 28533425, 2017). "We compared the methylation status of three genes, SOX17, CST6 and BRMS1 in primary tumours, corresponding CTCs and ctDNA in 153 breast cancer patients and healthy individuals, by using real time methylation specific PCR." (PMID 29069768, 2017). "The present meta-analysis investigated the correlation between BRMS1 and the clinico-pathological features of breast cancer including LNM, TNF stages, tumor size, histological grade, pathological type, ER, PR, OS, and RFS." (PMID 28533425, 2017). "Chimonidou and colleagues demonstrated in three studies that methylation status of three tumor-associated genes (CST6, BRMS1, and SOX17) can be detected in circulating tumor cells of breast cancer patients." (PMID 29190932, 2017). "Current study illustrates that BRMS1 protein expression in breast cancer tissue is significantly lesser than normal tissue." (PMID 28533425, 2017). "BRMS1 is also an inhibitor of metastasis in ovarian cancer, bladder cancer, non-small cell lung cancer, melanoma, and breast cancer." (PMID 28533425, 2017). "BRMS1 mRNA expression has been shown to be markedly reduced in melanoma, breast cancer, ovarian cancer and non-small cell lung cancer cell lines, while stable overexpression of BRMS1 in these cell lines significantly inhibited their metastatic potential." (PMID 29069768, 2017). "BRMS1 protein in all three major types of breast cancer was lower than that of control tissues respectively." (PMID 28533425, 2017). "BRMS1 promoter methylation was detected in 19/42 (45.2%) patients with early breast cancer and 5/32 (15.6%) metastatic patients." (PMID 29069768, 2017). "Further investigation showed that fascin up-regulated NF-κ B activity, uPA, MMP-2 and MMP-9 expression, but down-regulated the expression and nuclear translocation of BRMS1, resulting in a higher ability of breast cancer cells to migrate and invade." (PMID 29285273, 2017). "One study, involving 161 breast carcinoma specimens, showed that the level of BRMS1 mRNA expression was marginally higher in ERα-positive group than in the ERα-negative group." (PMID 26821020, 2016).
breast carcinoma (continued). "Here, we report for the first time, that BRMS1 is a downstream target in ER positive breast cancer cells and that its expression is modulated by the ERα in the presence of estrogen or an ERα agonist." (PMID 26821020, 2016). "Our results showed that estrogen increased the transcription and expression of BRMS1 in the ERα positive breast cancer cell line, MCF-7." (PMID 26821020, 2016). "In the present study, we provide evidence that in addition to TWIST1, BRMS1 attenuates breast cancer cell invasion through downregulating Snail expression." (PMID 26520789, 2015). "In the present study, we observed that BRMS1 efficiently inhibited TGF-β1-induced breast cancer cell EMT and invasiveness by downregulating not only TWIST1 but also Snail expression." (PMID 26520789, 2015). "In our effort to elucidate the mechanism how Cullin3 modulates migration in breast cancer cells, we identified BRMS1 as an effective mediator of Cullin3-induced migration." (PMID 26544623, 2015). "Recent studies suggest that BRMS1 suppresses breast cancer cell metastasis through modulating cancer cell EMT." (PMID 26520789, 2015). "In human breast carcinoma cell lines, it has been shown that the degree of metastasis suppression generally correlates with the level of BRMS1 protein expression." (PMID 24688598, 2014). "In human breast carcinoma cell lines, for example, it was shown that the amount of BRMS1 mRNA present in the cell lines is inversely correlated with their metastatic potential." (PMID 24688598, 2014). "BRMS1 is an MSG first described in human breast cancer and it has been correlated with decreased metastatic disease in many other tumours." (PMID 24688598, 2014). "Further studies showed that higher BRMS1 expression correlates with a better prognosis of breast carcinomas patients, and BRMS1 is active in suppressing breast carcinoma metastasis both in vitro and in vivo." (PMID 22927944, 2012). "Breast cancer metastasis suppressor 1 (BRMS1) was originally identified as an active metastasis suppressor in human breast cancer." (PMID 22927944, 2012). "In the breast carcinoma model, BRMS1 mainly functions in regulating cell apoptosis, gap junctional intercellular communication and cell invasion, but does not affect cell growth or cell adhesion." (PMID 22927944, 2012). "In breast cancer, BRMS1 expression was higher in the neo11/435 metastasis-suppressed hybrid cell line than in the MDA-MB-435 parental line, which is a highly metastatic breast cancer cell line in vitro." (PMID 22931099, 2012). "The BRMS1 transfection also resulted in downregulated expression of miR-10b and RhoC, which suggests that miR-10b does affect the metastasis of breast cancer cells." (PMID 23202960, 2012). "Recently, an increasing number of studies have demonstrated the potential of using BRMS1 as a prognostic marker and therapeutic target for breast cancer, ovarian cancer, melanoma and NSCLC." (PMID 22200669, 2012). "Among metastasis suppressors, breast cancer metastasis suppressor 1 (BRMS1) was originally shown to functionally suppress the metastatic capacities of breast cancer cells." (PMID 22200669, 2012). "Further research on the role of miR-10b in the metastasis of breast cancer showed that downregulation of miR-10b is one of the mechanisms by which breast cancer metastasis suppressor 1 (BRMS1) inhibits metastasis." (PMID 23202960, 2012). "Though the initial reports stemmed from research performed on breast cancer, convincing independent studies on suppression of melanoma metastasis by BRMS1 were described very early." (PMID 22356729, 2012). "BRMS1 is a metastasis suppressor that affects multiple steps in the metastasis cascade of breast carcinoma, acting through different mechanisms which involve various genes whose function is related to the control of the metastatic potential." (PMID 22453030, 2012).
breast carcinoma (continued). "Further studies showed that BRMS1 is not only a metastasis suppressor gene in breast cancer models but also in various other cancers, such as melanoma and ovarian cancer." (PMID 22200669, 2012). "Osteopontin (OPN), also known as secreted phosphoprotein 1 (SPP1) and originally identified in osteoblasts, is transcriptionally regulated by BRMS1 in breast cancer." (PMID 22927944, 2012). "BRMS1 was also shown to inhibit metastasis in xenograft models of breast cancer, melanoma and ovarian carcinoma." (PMID 22931099, 2012). "BRMS1 mRNA expression was downregulated in breast tumor tissues and in breast cancer brain metastases." (PMID 22200669, 2012). "BRMS1 has previously been demonstrated to be a metastasis-suppressing gene in breast cancer, melanoma, ovarian cancer, bladder cancer and lung cancer." (PMID 22931099, 2012). "BRMS1 was initially identified in the chromosome region 11q13-q14, which exhibits a high frequency of deletion in late-stage, metastatic breast carcinomas patients." (PMID 22927944, 2012). "Breast cancer metastasis suppressor 1 (BRMS1) is a metastasis suppressor that was first identified in breast cancer." (PMID 22927944, 2012). "Examining the relationship between BRMS1 and fascin in our breast cancer patient samples demonstrated variations in the intensity and subcellular distribution of BRMS1." (PMID 22076152, 2011). "BRMS1 negatively regulates uPA expression through inhibition of the NF-κB activity in breast cancer and melanoma cells." (PMID 22076152, 2011). "SiFascin breast cancer cells showed significantly enhanced BRMS1 RNA and protein expression compared with SiCon, consistent with the role of fascin in enhancing breast cancer metastatic potential." (PMID 22076152, 2011). "The BRMS1 gene product seems to act as a transcriptional regulator of diverse genes, and is capable to reduce the metastatic potential of human breast cancer and melanoma cell lines." (PMID 19405953, 2009). "Breast cancer metastasis suppressor 1 (BRMS1) has been shown to suppress metastasis of metastatic human breast cancer and melanoma lines as well as mouse mammary cancers." (PMID 17227585, 2007). "Interestingly, we had previously demonstrated an inverse relationship between fascin and nuclear BRMS1 in breast cancer patients." (PMID 39063133, 2024). "However, a similar observation has been made in a cohort of breast cancer patients, where BRMS1 mRNA levels in breast cancer cells were significantly higher than in normal epithelial cells and in hypopharyngeal cancer." (PMID 37296870, 2023). "Moreover, BRMS1 contributes to suppressing metastasis in various cancer cells by elevating miRNA-146a expression within metastatic breast cancer cells." (PMID 37628949, 2023). "BRMS1 plays the role of a suppressor gene as initially demonstrated in breast cancer cells." (PMID 36012171, 2022). "For assessing whether MREs could be used for the specific expression of exogenous gene(BRMS1) in metastatic breast cancer cells, a reporter plasmid includingluciferase regulated by their MREs was successfully constructed." (PMID 34096224, 2021). "BRMS1 was initially identified in breast carcinoma and suppressed breast cancer metastasis." (PMID 34054958, 2021). "This project was carried out to determine whether the combinations of miR-31 and BRMS1 genes are able to enhance the capability of repressing the claudin-low breast cancer cell (MDA-MB-231) invasion." (PMID 32405371, 2020). "Finally, there is little discussion about the expressions of BRMS1 in in-depth classification of breast cancer, like triple-negative breast cancer (TNBC) and ER+ tumors, a potentially impactful limitation of the analysis that required further investigation." (PMID 28533425, 2017). "In TNM stages 1 and 2, we found that since the expression of BRMS1 protein was drastically higher compared with TNM stages 3 and 4, breast cancer progression might be correlated with low expression of BRMS1 protein." (PMID 28533425, 2017).